IDO1 (indoleamine 2,3-dioxygenase 1)
Diseases named in the same sentence as IDO1 in open-access papers (continued):
Sharing a sentence is not in itself a finding about the gene and the disease.
tumor (continued). "IDO1, the principal rate-limiting enzyme catalyzing tryptophan (TRP) metabolism along the kynurenine pathway outside the liver, has been extensively studied in the context of the tumor microenvironment." (PMID 40715093, 2025). "Furthermore, upregulation of PD-L1, IDO1 expression, and TGF-β signaling can dampen anti-tumor immune responses and limit the efficacy of ICIs." (PMID 40708940, 2025). "In this study, IDO1 and IL4I1 were expressed by HNSCC tumor cells in the TMA of 402 patients." (PMID 40332319, 2025). "The scaffold can be loaded with tumor antigens, toll-like receptor (TLR) agonists, adjuvants, GM-CSF, metabolic inhibitors (indoleamine 2,3-dioxygenase 1, IDO1 inhibitor), and various chemoattractants to recruit and activate multiple DC subsets for a prolonged period." (PMID 41176596, 2025). "In CRC, tryptophan (Trp) transporters (SLC7A5, SLC1A5) and key components of the kynurenine (Kyn) metabolic pathway (TDO2, IDO1, AFMID) are significantly upregulated, a molecular adaptation that enhances Trp uptake and catabolism to fuel tumor cell proliferation." (PMID 41488637, 2025). "Subsequently, all factors identified from the univariate analysis were included in the multivariate analysis: age, PDCD1/CD27 ratio, PDCD1/TNFSF4 ratio, IDO1/TMIGD2 ratio, IDO1/TNFSF4 ratio, neoadjuvant treatment, initial weight of tumor, ER status, PR status, HER2 status, and TNM stage." (PMID 40061889, 2025). "These technological advancements position PROTACs as versatile tools for comprehensive IDO1 inhibition, capable of disrupting both metabolic and non-metabolic immunosuppressive pathways in the tumor microenvironment." (PMID 40894232, 2025). "In this study we investigated the expression of IDO-1 in two different cohorts of surgically-resected specimens of NSCLC, both in tumor cells and in tumor immune infiltrate, with specific correlation analyses of IDO-1 expression levels and clinical features of patients." (PMID 40475772, 2025). "Earlier tumour stages may involve different KYN-pathway dynamics, including IDO1- or TDO2-driven KYN production." (PMID 40471422, 2025). "IDO1 and TDO2 are the first rate-limiting metalloenzymes that are responsible for the degradation from TRP to kynurenine, which is closely correlated to the failure of anticancer immunotherapies and tumor progression through the activation of AhR." (PMID 41255573, 2025). "In the tumor microenvironment (TME), expression of key enzymes—IDO1 and TDO—is markedly elevated." (PMID 40666095, 2025). "In terms of tumor immune suppression, past studies have focused greatly on the enzymatic function of IDO1, but its non‐enzymatic function should not be overlooked." (PMID 40103267, 2025). "Moreover, there is emerging evidence that H2S can alter tumor immunity through suppression of the GBM-permissive indoleamine 2,3 dioxygenase 1 (IDO1), an enzyme that normally enhances immune suppression in the tumor microenvironment." (PMID 40675856, 2025). "Indoleamine 2,3-dioxygenase 1 (IDO 1)-driven tryptophan catabolism via the kynurenine pathway creates an immunosuppressive environment that facilitates immune evasion and promotes tumor progression." (PMID 40717985, 2025). "Recent studies have shown that Wnt5a, a non-canonical Wnt ligand, activates the IDO1 pathway, thereby reinforcing immune suppression while sustaining metabolic adaptations that support tumor survival and proliferation." (PMID 40917745, 2025).
tumor (continued). "In addition, an experimental validation was also carried out; the exogenous addition of recombinant IFN-γ (50 ng/mL) was sufficient to induce a significant upregulation of Ido1 at both transcriptional and translational levels in MC38 tumor cells." (PMID 41129257, 2025). "Another study did not focus on the IDO1 expression in tumor cells, but found IDO1 expressing immune cells, especially macrophages, to be more abundant in advanced stages of OSCC and a reduced progression-free survival." (PMID 40332319, 2025). "The synthetic lethal screen with metabolic inhibitors identified preferential suppression of tumor cell proliferation by a combination of (R)-GNE-140 (an inhibitor of the lactate dehydrogenases (LDH) A/B) and the IDO1 inhibitor BMS-986205, which is currently tested in clinical trials." (PMID 40550880, 2025). "Single-cell transcriptomics has revealed heterogeneity in IDO1/TDO2 expression across tumor and stromal compartments, demonstrating that localized tryptophan metabolism can differentially shape immune niches within the same tumor." (PMID 41562065, 2025). "There may also be tumor-specific differences in BrM, for example, NKG2D ligand expression was inversely correlated to the immunosuppressive factor IDO1 expression in BrM." (PMID 40849493, 2025). "Similarly to IDO1-driven tryptophan depletion, ARG1-mediated arginine depletion impairs the metabolic fitness and differentiation of tumor infiltrating lymphocytes (TILs)." (PMID 40507361, 2025). "Specifically, IDO1 catabolic activity can be assessed using the serum Kyn/Trp Ratio (KTR), which has been shown to serve as an independent prognostic factor for various tumour types (Ref." (PMID 40040508, 2025). "This “extrinsic” effect, driven by catalytic inhibition of IDO1, reshapes the TME and may disrupt IDO1-dependent immune evasion by the tumor." (PMID 41262240, 2025). "The IHC staining results of 30 tumor tissue samples from BLCA patients provided by Yanbian University Hospital also showed a positive correlation between the expression of CD206, HCK, and IDO1." (PMID 41438182, 2025). "Recent findings on the non-enzymatic function of IDO1 within the tumor cells underscore the urgent need to develop an effective approach capable of inhibiting IDO1’s dual function, including its enzymatic and signaling activities." (PMID 41262240, 2025). "Mechanistically, IDO-1 can trigger cell cycle arrest in the G1 phase or autophagy in T cells by activation of amino acid-sensitive kinase GCN2 and inhibition of the mTOR signaling pathway via tryptophan–kynurenine metabolic pathway in tumor microenvironment." (PMID 37981615, 2024). "Conversely, several factors contribute to NK cell dysfunction, such as severe hypoxia, the accumulation of tumor cell metabolites, alterations in inhibitory receptors or NK inhibitors, and the presence of molecules like TGFβ, prostaglandin E2 (PGE2), or indoleamine 2,3-dioxygenase 1 (IDO1)." (PMID 39000296, 2024). "Moreover, our research revealed a compelling connection between IDO1 and PD-1, particularly coexpressed on TAMs through comprehensive exploration of TME and multiplexed immunofluorescence validation in tumour samples." (PMID 39351094, 2024). "Their tumor tissues also had higher IDO1 and FoxP3 expression than tumor tissues from PS-conditioned medium-treated or non-treated mice." (PMID 38540186, 2024). "Mice receiving CISE@Gel exhibited a prominent decline in tumor growth, which was far more effective than CS@Gel and CIS@Gel, which may be attributed to the superimposed effects of IDO1 silencing and CD62E‐mediated tumor targeting." (PMID 38884220, 2024). "Therefore, the intricate relationship between IDO1 levels and clinical outcomes can be attributed to various factors such as age, sex, tumor type, follow-up time, study quality, IDO1/CD8 ratio, and IDO1 expression site." (PMID 38780888, 2024).
tumor (continued). "Both the lack of tryptophan and the tumor progression itself can be consequences of an immune escape mechanism mediated by the expression of IDO1 (indoleamine-2,3-dioxygenase 1)." (PMID 38731892, 2024). "IDO1 was observed in the cytoplasm of the tumor cells as a finely granular or homogeneous nongranular stain." (PMID 39061522, 2024). "PDT could efficiently induce ICD to recruit CD8+ T cells into the tumor region but inevitably drives COX‐2 and downstream PGE2 and IDO1 expression." (PMID 38224203, 2024). "A non-enzymatic role of IDO1 was also described in the TME where it promoted tumor progression independently of its catalytic activity." (PMID 38333210, 2024). "Furthermore, the endogenous AhR kynurenine is produced through the metabolism of tryptophan by IDO1 which is induced in stromal cells, or by TDO2 which can be up-regulated in tumor cells and the tumor stroma." (PMID 39200369, 2024). "Recent evidence and the current study highlight a new prospective on the IDO1 target in cancer immunotherapy, by elucidating the non-enzymatic key role of IDO1 in tumor progression." (PMID 38333210, 2024). "Of the six IDO1-negative tumors, five tumors represented cold tumors, and one was classified as an altered-immunosuppressed tumor." (PMID 39061522, 2024). "Here, based on bioinformatics analysis derived from TCGA database and clinical sample validation, we identified that altered tumor mechanics in the TPME and abnormal cellular IDO1 metabolism are two major factors that contribute to ccRCC aggression and compromise treatment efficacy." (PMID 38884220, 2024). "IDO enzymes (IDO1 and 2), responsible for Tryptophan (TRP) degradation and Kynurenines (KYN) production, are key factors in the tolerance process, immune escape mechanisms and tumor-induced immunosuppression." (PMID 38791968, 2024). "Since the enzymatic activity of IDO1 and TDO2 have been shown to contribute to the immune-suppressive condition in the tumor microenvironment (reviewed in9), small molecule inhibitors are regarded as a therapeutic option to reinvigorate anti-tumor immunity." (PMID 39537789, 2024). "There were no apparent differences in the histologic features of carcinomas with or without IDO1 expression in tumor cells." (PMID 39061522, 2024). "Alternative IDO1-based therapies are expected to emerge by selectively targeting the non-enzymatic function of IDO1 in tumor cells once the signaling pathway mediated by IDO1 is fully elucidated." (PMID 38333210, 2024). "Overall, our findings unveiled a new mechanism of action of epacadostat on IDO1 target, repositioning the catalytic inhibitor as a stabilizer of the apo-form of IDO1, still capable of transducing a pro-tumorigenic pathway in SKOV-3 tumor." (PMID 38333210, 2024). "Additionally, inhibitors of several key metabolic enzymes, such as IDH1(Isocitrate Dehydrogenase 1), IDO1((Indoleamine 2,3-dioxygenase 1), GPX4(Glutathione Peroxidase 4), and NAMPT(Nicotinamide phosphoribosyltransferase), have shown good anti-tumor effects." (PMID 39578429, 2024). "We also observed increased Ido1 but not Ifng expression in normal tissue adjacent to tumours demonstrating this effect is not restricted to tumour cells." (PMID 39242821, 2024). "Regrettably, the degree of IDO1 inhibition was evaluated in neither plasma nor tumor biopsies of patients enrolled in the ECHO-301 trial." (PMID 39211039, 2024). "Tumor cells with and without IDO1 expression were detected within all tumor areas, including the tumor center and the invasive margin." (PMID 39061522, 2024). "Notably, ablation of host IDO1 expression also induces loss of IDO1 inhibitor efficacy in different tumor models, which would be suggestive of a suppressive role for host IDO1, although deficiency in host IDO1 itself paradoxically does not alter tumor growth in these models." (PMID 39211039, 2024).
tumor (continued). "Thus, immunosuppressive tumor cytokines and AhR stimulation promote CD83 downregulation and generation of CD83- IDO1+LCs (immature tolerogenic LCs) and/or CD83- IDO1-LCs (real immature LCs)." (PMID 38791968, 2024). "Tryptophan catabolism by IDO1 and TDO2 is critical within the tumour microenvironment (TME) as lowered tryptophan and raised kynurenine each confers an anti-immune response, by attenuating CD8+ Tcell infiltration, and promoting regulatory CD4+ cell differentiation." (PMID 39048947, 2024). "However, to our surprise, our results demonstrated that EPHX4 was significantly negatively correlated with CD274, PDCD1, IDO1 and LAG3, which all attenuate anti-tumor immunity and escape destruction by the immune system." (PMID 38663041, 2024). "Furthermore, the aberrant IDO1 expression was connected to the TMB, MSI, MMR, drug sensitivity, immune cells infiltrating, and tumor immune microenvironment across a variety of cancer types." (PMID 38539263, 2024). "However, prolonged exposure to interferon-gamma transforms teammates into adversaries, producing pro-tumorigenic effects through immunosuppression (PDL1, IDO1, Fas, and FASL), angiogenesis (CXCL9, CXCL10, CXCL11, IDO1, and iNOS), and tumor cell proliferation." (PMID 39835116, 2024). "Enhanced expression of IDO1 and TDO2 leads to greater catabolism of tryptophan leading to raised levels of the tryptophan metabolite kynurenine in the tumour, and thereby enhancing activation of the aryl hydrocarbon receptor (AhR) for which kynurenine is an endogenous ligand." (PMID 39048947, 2024). "Therefore, cancer trends showed a high expression of IDO1 and/or TDO2 to catabolize TRY, generating abundant KYN that further activates AHR and its targets for the sake of tumor progression." (PMID 38347841, 2024). "Studies reveal that IDO1 is an immunosuppressant in the TME and related to tumor progression." (PMID 39239507, 2024). "In response to these observed phenomena, researchers have developed a range of IDO1-selective inhibitors, including Epacadostat, Navoximod, BMS-986205, etc., currently undergoing clinical trials, these inhibitors hold promise for future tumor therapy." (PMID 38883986, 2024). "IDO1 is endogenously expressed in immune and non-immune cells and tissues, as well as in neoplastic cells and in the tumor microenvironment, in a dynamic balance between a holo- and an apo-conformation." (PMID 39594642, 2024). "However, IFN-γ not only leads to feedback suppression during the regulation of immune response but also up-regulates and induces the expression of certain immunosuppressive molecules (such as IDO1, MHCII), thus weakening the anti-tumor immune effect." (PMID 38388534, 2024). "Tryptophan through its degradation by indoleamine-2,3-dioxygenase 1 (IDO1) and tryptophan-2,3-dioxygenase 2 (TDO2) to kynurenine has emerged as an important metabolic regulator of tumor progression, immune suppression and immune tolerance in the tumor microenvironment." (PMID 39450255, 2024). "Accordingly, the inducible or constitutive IDO1 expression in cancer correlates with a negative prognosis for patients, representing one of the critical tumor-escape mechanisms." (PMID 38333210, 2024). "Accordingly, IDO1 expression in SLN currently represents a negative prognostic factor, and IDO1 inhibitors are a focus of research, potentially reverting tumor tolerance." (PMID 38791968, 2024). "While IDO1 and PD-1 have non-overlapping mechanisms of action, it is rare that an agent with no demonstrated single agent activity results in synergistic anti-tumor efficacy when used in combination with an effective agent." (PMID 39054487, 2024). "IDO1-negative carcinomas (n = 6): The maximal stromal TILs at the invasive margin ranged from 2 to 15% and from 0 to 30% in the central tumor area." (PMID 39061522, 2024).
tumor (continued). "In addition, indoleamine 2,3-dioxygenase 1 (IDO1), an interferon-gamma (IFN-γ)-induced enzyme, promotes the infiltration of regulatory T cells (Tregs) and MDSCs in the tumor microenvironment (TME)." (PMID 38351314, 2024). "The chemotherapeutic drug paclitaxel has been shown to induce immunogenic cell death (ICD), whereas inhibitors of the indoleamine 2,3- dioxygenase 1 (IDO1) enzyme, whose expression is shared in immune regulatory and tumor cells, have been revealed to enhance the anti-tumor immune response." (PMID 38591056, 2024). "Adjacent T-cell-rich regions had higher levels of key proteins such as CD45RO and several immune suppressive factors (IDO1, VISTA, TIM-3, LAG-3 and ICOS), which may result in less T-cell expansion in regions close to the tumor." (PMID 39001353, 2024). "Activation of IDO1 signaling in the tumor cell plays a pro-tumorigenic role rather than immunoregulatory functions." (PMID 38333210, 2024). "A phase I trial assessing the IDO1 inhibitor navoximod with the PD-L1 inhibitor atezolizumab showed antitumor activity in various tumor types, including NSCLC; however, no clear benefit of adding navoximod was seen." (PMID 39054462, 2024). "The depletion of tryptophan by IDO1 leads to the suppression of cytotoxic T cells, differentiation of naïve T cells to immunosuppressive Treg cells, induction of immunosuppressive MDSC activity, and recruitment of tumor vasculature." (PMID 37631380, 2023). "We used TISIDB database to predict and analyze the correlation between CHSY1 expression and immune factors including PD-L1, PD1, LAG3, IDO1 and CTLA4, so that we could observe the interaction between CHSY1 and the CRC tumor microenvironment." (PMID 37749638, 2023). "In addition, we examined the expression levels of PD1, PDL1, CTLA4, TGFB1, TIGIT, IDO1, and LAG3 in 51 tumor samples." (PMID 37928532, 2023). "Combination of targeting IDO1 and PDL1 with CAR-T cells serves as a dual targeting agent against tumor cells and MDSCs in TME and enhances immunotherapeutic potential of CAR-T cells against tumor." (PMID 37006306, 2023). "It has been shown that the tumor-derived cytokine CCL20 upregulates IDO expression, and IDO also inhibits CD8+ T cell responses and induces tumor immune evasion, so it is highly likely that the strong rise of CCL20 in PBK overexpression inhibits CD8+ T cells via IDO1." (PMID 37993518, 2023). "Above all, IDO1 and COX2 have attracted attention in cancer research and may be promising prognostic and therapeutic biomarkers of tumor tissues." (PMID 36983678, 2023). "PD-L1 and IDO-1 induce apoptosis in T-cells, and therefore it was suggested that their inhibition may be useful to increase the success of TIL-related tumor immunotherapy." (PMID 37958417, 2023). "In addition, IFNγ also increases the expression of checkpoint inhibitors, such as indoleamine-2,3-dioxygenase 1 (IDO1) and CTLA-4, leading to enhanced tumor growth." (PMID 37190141, 2023). "IDO1 is highly and constitutively expressed in NSCLC patients and acts as an immune checkpoint induced by potent mediators such as interferon-γ (IFN-γ), transforming growth factor-β (TGF-β), and other proinflammatory signals in the tumor microenvironment." (PMID 36824664, 2023). "Indolamine 2,3-dioxygenase 1 (IDO1) is an intracellular enzyme produced by tumor cells, MDSCs and TAMs that metabolizes tryptophan, negatively impacts effector T cell function and enhances Treg activity, thereby inhibiting the anti-tumor immune response." (PMID 38275827, 2023). "In addition, regulatory DCs also highly express IDO1 in HCC, which can induce tumor-infiltrating Treg cell proliferation." (PMID 37383234, 2023). "Although patients with high IDO1 expressing tumours (n = 30) were found to have longer progression free survival and overall survival than patients with low IDO1 expressing tumours (n = 22), the differences were not statistically significant." (PMID 37041200, 2023).